PRDM5 (PR/SET domain 5)
Diseases named in the same sentence as PRDM5 in open-access papers (continued):
Sharing a sentence is not in itself a finding about the gene and the disease.
polyp (1 paper, 2015). A usually exophytic mass attached to the underlying tissue by a broad base or a thin stalk. "PRDM5 protein expression was also examined in cancer and polyp subgroups, and PRDM5 mutation frequency was investigated using a publicly available database." (PMID 25613750, 2015). "PRDM5 was methylated in 2 of each of the three serrated polyp subtypes to give an overall methylation rate of 10% (6/59) in the serrated polyps compared to the lack of methylation in both subtypes of conventional polyps (0/40) (p = 0.08)." (PMID 25613750, 2015). "The average PMR of methylated PRDM5 was significantly higher in all serrated polyp subtypes compared to the conventional polyps (p = 0.01)." (PMID 25613750, 2015). "Furthermore, PRDM5 protein levels were substantially reduced across both serrated and conventional polyp types and more so in BRAF mutant and wild type cancers." (PMID 25613750, 2015). "Interestingly, PRDM5 protein expression was substantially reduced in all polyp types and more so in cancers which also indicates early and increasing PRDM5 down-regulation with disease progression." (PMID 25613750, 2015). "Due to the low rate of PRDM5 mutation found, this type of analysis was not extended to this study’s cancer or polyp cohorts." (PMID 25613750, 2015).
tumor (29 papers, 2009 to 2025). "As a transcriptional regulator, PRDM5 has been implicated as a tumor suppressor and to be silenced in several cancers." (PMID 36127737, 2023). "PRDM5 encodes PR domain zinc finger protein 5 (PRDM5), a transcription factor that was identified as a putative tumor suppressor gene in several cancers but has also been shown to regulate transcription of collagen and other ECM genes." (PMID 34712265, 2021). "PRDM5 silencing is also linked to the accumulation of active β-catenin in tumor cells, which leads to constitutive activation of WNT/β-catenin signaling." (PMID 22087297, 2011). "In addition, the promoter activity of SOCS1 was positively regulated by PRDM5, implying the possible mechanism underlying the tumor suppressive activities of PRDM5 in LUAD cell proliferation." (PMID 36127737, 2023). "This pharmacologic demethylation restored PRDM5 expression in all silenced cell lines, accompanied by the increase of demethylated promoter alleles, indicating that PRDM5 silencing in tumor cells was directly mediated by promoter methylation." (PMID 22087297, 2011). "Previous report showed that ectopic PRDM5 expression caused cell cycle G2/M arrest and induced apoptosis in tumor cells, while the molecular mechanisms remain unknown." (PMID 22087297, 2011). "As an epigenetic regulator and a transcription factor, PRDM5 should exert its tumor suppressive functions through transcription and cell signaling." (PMID 36127737, 2023). "Recently, several studies have revealed the role of PRDM5 in different types of cancer, demonstrating that it functions as a tumor suppressor to regulate its target genes at the transcriptional level or by interacting with epigenetic regulators." (PMID 36127737, 2023). "The PRDM5 protein was found to have a variety of functions as a transcription factor, being involved as a tumor suppressor gene in epithelial cancer and as a regulator of extracellular matrix development in corneal and bone cells." (PMID 37629506, 2023). "PRDM5 is considered a tumor suppressor in several types of solid tumors and is involved in multiple cellular processes." (PMID 36127737, 2023). "PRDM5 expression (p = 0.034), tumor diameter (p < 0.001), clinical stage (p < 0.001) and vascular invasion (P=0.048) were identified as important risk factors for OS." (PMID 34659579, 2021). "Although no animal models have been generated to study BCS pathogenesis, two independent studies investigated the role of PRDM5 in zebrafish larvae as a putative tumor suppressor and during craniofacial development." (PMID 34712265, 2021). "In this study, we verified that the silencing of PRDM5 in GC was due to the methylation of its promoter, and confirmed its tumor suppressive effect in GC." (PMID 34659579, 2021). "In this study, we demonstrated that PRDM5 plays a role as a tumor suppressor in GC, and its down-regulation in GC patients is partly caused by DNA hypermethylation." (PMID 34659579, 2021). "Through univariate and multivariate regression analysis, we found that PRDM5 expression is the same as clinical stage and tumor size, which are independent prognostic factors of GC." (PMID 34659579, 2021). "PRDM5 has been shown to inhibit tumor growth in vitro in patients with advanced GC, but its specific clinical significance and the critical roles in GC have rarely been probed." (PMID 34659579, 2021). "In vitro, ectopical expression of PRDM5 inhibited the growth of tumor cells, while knockdown of PRDM5 increased the proliferation and migration of tumor cells." (PMID 34659579, 2021). "In multivariate Cox analysis, PRDM5 expression (p = 0.043), tumor diameters (p=0.024) and clinical stage (p < 0.001) were found to be independent prognostic factors for OS." (PMID 34659579, 2021). "In terms of mechanism, it is far from enough to understand the role of PRDM5 as a tumor suppressor in GC." (PMID 34659579, 2021).
tumor (continued). "Afterwards, other literature data confirmed the proposed role of PRDM5 as a tumor suppressor since it is frequently downregulated in several malignancies." (PMID 32290321, 2020). "PRDM5 has been proposed as a tumor suppressor frequently silenced in multiple human tumors that antagonizes WNT/β−catenin signaling and oncogene expression." (PMID 32630147, 2020). "This evidence infers that PRDM5 acts as an oncogene in MM, which contrasts with its previously reported tumor suppressor role in solid tumors." (PMID 32820006, 2020). "With a high frequency of DNA promoter hypermethylation, PRDM5 is primarily considered as a tumor suppressor in solid tumors." (PMID 31119897, 2019). "SMYD2, EZH2, and SUV420H2 were up‐regulated and SETD7, PRDM1, PRDM8, PRDM6, and PRDM5 were down‐regulated in tumor." (PMID 30984543, 2019). "PRDM5 protein overexpression drove AML progression by significantly enhancing the tumor growth, proliferation, and migration in vitro." (PMID 31119897, 2019). "Functional studies have identified PRDM5 as a tumour suppressor gene due to its role in suppressing cell growth and proliferation, in regulation of the cell cycle at the G2/M checkpoint and as a heat shock responsive gene." (PMID 25613750, 2015). "Frequent silencing of PRDM5 in multiple cancer cell lines and primary tumors indicated that PRDM5 likely functions as a tumor suppressor." (PMID 22087297, 2011). "PRDM5 suppresses tumor cell growth through antagonizing WNT/β-catenin signaling and suppressing multiple oncogenes expression." (PMID 22087297, 2011). "Ectopic expression of PRDM5 leads to G2/M arrest and apoptosis of tumor cells, although its molecular mechanism is still unclear." (PMID 22087297, 2011). "We further examined the expression changes of multiple oncogenes and tumor suppressor genes after ectopic PRDM5 expression in both normal and tumor cell lines (HEK293 and HONE1)." (PMID 22087297, 2011). "Consistently, knock-down of endogenous PRDM5 using siRNA in HEK293 cells significantly increased the cell proliferation rate, suggesting that PRDM5 does function as a tumor suppressor." (PMID 22087297, 2011). "PRDM5 functions as a tumor suppressor at least partially through antagonizing aberrant WNT/β-catenin signaling and oncogene expression." (PMID 22087297, 2011). "As a zinc finger transcription factor and epigenetic modifier, PRDM5 should exert its tumor suppressive functions through modulating cell signaling and gene transcription." (PMID 22087297, 2011). "Taken together, these results revealed a strong correlation between PRDM5 promoter CpG methylation and its transcriptional silencing in tumor cell lines." (PMID 22087297, 2011). "We studied a recently identified PRDM member PRDM5 for its epigenetic abnormality and tumor suppressive functions in multiple tumorigeneses." (PMID 22087297, 2011). "Ectopic expression of PRDM5 inhibited tumor cell clonogenicity, at least partially through antagonizing WNT/β-catenin signaling and oncogene expression such as CDK4, TWIST1, and MDM2." (PMID 22087297, 2011). "Our study indicates that if the epigenetic modifier PRDM5 is inactivated in tumor cells, its repression to target oncogenes would be released and thereby contributing to tumor initiation and progression." (PMID 22087297, 2011). "PRDM5 is a recently identified family member that functions as a transcriptional repressor and behaves as a putative tumor suppressor in different types of cancer." (PMID 19169355, 2009). "The definition of PRDM5 as candidate tumor suppressor derives from its frequent inactivation in human cancers and from its ability to impair cell growth and enhance apoptosis." (PMID 19169355, 2009). "Within this potential FFL, TEAD4 may drive the expression of miR-3662, which in turn suppresses PRDM5, tipping the balance toward tumor-promoting gene expression." (PMID 40862714, 2025).
tumor (continued). "In addition to the findings of deregulation of PRDM5 in numbers of solid tumor types, our study also showed that PRDM5 acted as a tumor suppressor in LUAD." (PMID 36127737, 2023). "On the basis of our results, PRDM5 may exert its tumor suppressive function by regulating cell proliferation rather than the cell cycle in LUAD." (PMID 36127737, 2023). "This indicates that PRDM5 down-regulation may start in the early stages of tumor development and continue with the development of the disease." (PMID 35799142, 2022). "It was found that the expression of PRDM5 in adjacent tissues was higher than in tumor tissues." (PMID 35799142, 2022). "And we found that the protein expression of PRDM5 was generally inhibited in tumor tissues." (PMID 34659579, 2021). "PRDM5 expression was significantly correlated with tumor stage and histological type." (PMID 34659579, 2021). "Similarly, PRDM5 was frequently silenced by promoter methylation in multiple cancer cell lines and tumor specimens, including nasopharyngeal, esophageal, gastric, cervical, and hepatocellular carcinoma." (PMID 32290321, 2020). "Overall, these data suggest that PRDM5 is a tumor suppressor in several human cancer types where it could represent a molecular marker for diagnosis and prognosis and a promising target for their therapy." (PMID 32290321, 2020). "Moreover, its tumor suppressor function was corroborated by the G2/M arrest and apoptosis of tumor cells upon infection of a recombinant adenovirus expressing PRDM5." (PMID 32290321, 2020). "Since its first description, PRDM5 has been considered to have a tumor suppressor role." (PMID 32290321, 2020). "Moreover, the inspection of gross tumor morphology showed a significant increase in the size and volume of tumors in PRDM5 OE group." (PMID 31119897, 2019). "While some such as PRDM2 and PRDM5 act as tumor suppressors, PRDM14 appears to be an oncogene." (PMID 31143550, 2019). "Furthermore, IHC revealed a higher level of PRDM5 and Ki67 in the tumor tissues of PRDM5 OE group than in those of CT group." (PMID 31119897, 2019). "Generally, PRDM5 acts as a tumor suppressor in most cancers." (PMID 27485778, 2016). "Our results demonstrate that tumor-specific promoter methylation represents the predominant mechanism of PRDM5 inactivation, although other mechanisms like gene micro-deletion or mutations might also exist." (PMID 22087297, 2011). "Frequent epigenetic silencing of PRDM5 is involved in multiple tumorigeneses, which could serve as a tumor biomarker." (PMID 22087297, 2011). "Ectopic PRDM5 expression significantly inhibited tumor cell clonogenicity, accompanied by the inhibition of TCF/β-catenin-dependent transcription and downregulation of CDK4, TWIST1 and MDM2 oncogenes, while knocking down of PRDM5 expression lead to increased cell proliferation." (PMID 22087297, 2011). "Thus, PRDM5 does exert its tumor suppressive functions through modulating WNT/ β-catenin signaling and the expression of multiple oncogenes as an epigenetic modifier." (PMID 22087297, 2011). "Although its precise biological function remains to be elucidated, inactivation of PRDM5 in different tumors suggests that it may behave as a tumor suppressor." (PMID 19169355, 2009). "Thus, we examined the effects of ectopic PRDM5 expression on tumor cell clonogenicity." (PMID 22087297, 2011). "Several PKMTs, including MLL3, PRDM2/RIZ, PRDM5, SMYD4, SUV4-20H2, and EEF1AKMT3, have been reported to exhibit tumor suppressor activities." (PMID 38036730, 2023). "Further exploration of the downstream pathways can reveal that PRDM5 can be regulated by WNT/β-catenin signal, and as an epigenetic modifier of the expression of a variety of cancer genes to exert its tumor suppressor effect." (PMID 35799142, 2022). "According to preliminary analysis, predictive factors include T status, vascular invasion, tumor grade, T stage, TNM staging, and PRDM5 staining, all of which were important prognostic indicators of OS." (PMID 35799142, 2022).
tumor (continued). "PRDM5 is a recently identified member of the PRDM family, which is composed of transcriptional regulators that modulate cellular processes and act as tumor suppressors." (PMID 33235205, 2020). "We further confirmed that the overexpression of PRDM5 in OCI‐AML3 cells and U937 cells promoted tumor proliferation in in vivo xenograft models." (PMID 31119897, 2019). "Since little is known about the functional role of PRDM5 in hematological malignancies, especially in AML, we investigated the role of PRDM5 in AML cell lines and identified PRDM5 as a tumor promoter in AML." (PMID 31119897, 2019). "Certain studies also reveal that PRDM5 expression downregulate several oncogenes like CDK4, TWIST1, and MDM2 thereby preventing tumour progression." (PMID 28144288, 2017). "PR domain zinc finger protein 5 (PRDM5), a member of the Kruppel-like zinc finger family is an important tumour suppressor gene and has been found to be methylated in gastric human carcinomas like." (PMID 28144288, 2017). "PRDM5 is a putative tumor suppressor through repression of WNT signaling, and known to be frequently silenced due to methylation across a number of other tumor types." (PMID 26963385, 2016). "PRDM2 is a member of the PRDM (PRDI-BF1 and RIZ domain containing) family, one member of which, PRDM5, down-regulates MDM2 gene expression to inhibit tumor cell clonogenicity and cell proliferation." (PMID 24124579, 2013). "Our finding that ectopic expression of PRDM5 leads to the inhibition of WNT/β-catenin signaling in tumor cells, probably through upregulating DKK1, DKK2, and WNT5A, suggests a novel mechanistic link between PRDM5 and WNT signaling in human tumorigenesis." (PMID 22087297, 2011). "Besides, the expression levels of PRDM5 were related to TNM staging, tumor differentiation, and vascular invasion in the combined data set." (PMID 35799142, 2022). "This study aimed to investigate whether PRDM5 might be a biomarker for the prognosis of ESCC and explore the mechanism in tumor development." (PMID 35799142, 2022). "PRDM5 is a recently identified member of the PRDM family and may function as a tumor suppressor in several types of cancer." (PMID 27485778, 2016). "PRDM5 antagonizes the Wnt/β-catenin signaling pathway in both normal and tumor cells." (PMID 34659579, 2021). "Our results, derived from gene expression data and functional studies in zebrafish development, suggest that PRDM5 may exert its tumor suppressor functions through negative modulation of wnt signaling." (PMID 19169355, 2009). "In A549 cell line, PRDM5 has been shown to be silenced by previous studies.Not surprisingly, we found that PRDM5 knockdown GC cells (AGS, SGC7901) significantly enhanced their proliferation ability and the ectopic expression of PRDM5 inhibited the proliferation of tumor cells." (PMID 34659579, 2021).
cancer (23 papers, 2009 to 2025). A tumor composed of atypical neoplastic, often pleomorphic cells that invade other tissues. "In total, 7 PRDM5 mutations were reported from 6 cancer samples (2.0% mutation rate) that were all BRAF wild type." (PMID 25613750, 2015). "In this study, methylated PRDM5 associated with presence of nuclear beta-catenin in the BRAF mutant/MSI cancers." (PMID 25613750, 2015). "Due to the greater rates of PRDM5 protein loss compared to methylation, other mechanisms are contributing to this silencing especially in the conventional polyps, as was seen in the cancer cohorts." (PMID 25613750, 2015). "The frequency of PRDM5 methylation also increased from serrated precursor lesion to BRAF mutant cancers at a similar proportion which suggests that PRDM5 methylation associates with advancing disease in cancers of the serrated pathway." (PMID 25613750, 2015). "Due to previous correlations of methylated PRDM5 with presence of active beta-catenin and exogenous PRDM5 causing a decrease in downstream Wnt reporter assays, presence of methylated PRDM5 and nuclear beta-catenin was assessed within the cancer cohorts." (PMID 25613750, 2015). "Silencing of PRDM5 by promoter hypermethylation has been demonstrated in several cancer types and PRDM5 loss results in upregulation of the Wnt pathway and increased cellular proliferation." (PMID 25613750, 2015). "Recent studies have highlighted the association of PRDM5 with the progression of human cancers." (PMID 35847370, 2022). "PRDM5 mutation was present in a small percentage of BRAF wild type cancers and this may be a cause of downregulation in this cancer subgroup." (PMID 25613750, 2015). "Furthermore, PRDM5 overexpression causes apoptosis of cancer cells." (PMID 32290321, 2020). "Furthermore, there was an association of PRDM5 methylation being more prevalent in BRAF mutant cancers presenting at late compared to early stages which further indicates epigenetic regulation of PRDM5 may influence disease progression in the serrated pathway." (PMID 25613750, 2015). "Ectopic PRDM5 expression can significantly reduce the colony formation efficiency of all cancer cells in monolayer culture." (PMID 35799142, 2022). "And expression of PRDM5 in gastric paracarcinoma and carcinoma tissues from 162 patients was detected by immunohistochemistry (IHC) and assessed the association with different clinicopathological features." (PMID 34659579, 2021). "PRDM5 has growth suppressive activities and is silenced in breast, ovarian, liver, lung, colon, and other cancers." (PMID 33330580, 2020). "Only when stratified for MSI status, was a correlation observed with a higher rate of nuclear beta-catenin in PRDM5 methylated compared to unmethylated BRAF mutant/MSI cancers (13/21, 62% vs 12/38, 32%) (p = 0.03)." (PMID 25613750, 2015). "We found the PRDM5 promoter region was substantially methylated in BRAF mutant cancers of the serrated pathway whereas minimal levels of methylation were detected in the BRAF wild type cancers of the traditional pathway." (PMID 25613750, 2015). "BRAF mutant cancers that had methylated PRDM5 were more likely to present at advanced stages compared to BRAF mutant cancers with unmethylated PRDM5 (AJCC stage III/IV: 29/65, 44.6% vs 31/105, 29.5%; p < 0.05)." (PMID 25613750, 2015). "Of the 10 cancers in the present study that retained PRDM5 protein expression, there was 90% concordance with these cancers being unmethylated." (PMID 25613750, 2015). "PRDM5 methylation was found to be an early event with progressive acquisition in BRAF mutant cancers of the serrated pathway." (PMID 25613750, 2015). "BRAF mutant cancers had significantly more frequent PRDM5 promoter methylation than BRAF wild type cancers (77/214,36% vs 4/122,3%; p<0.0001)." (PMID 25613750, 2015). "PRDM5 was methylated in 77/214 (36.0%) BRAF mutant cancers compared to 4/122 (3.3%) BRAF wild type cancers (p < 0.0001)." (PMID 25613750, 2015).